TERT (telomerase reverse transcriptase)
Diseases named in the same sentence as TERT in open-access papers (continued):
Sharing a sentence is not in itself a finding about the gene and the disease.
cancer (continued). "Furthermore, in accordance with other studies analyzing TERT mutations in cancer patients, we found that MIBC patients harboring TERT c.1-124C>T had a worse clinical outcome than those without the mutation, emphasizing the aggressive role of the TERT mutation in MIBC." (PMID 38068899, 2023). "A second mechanism involves the control of TERT gene expression by the Kruppel-like transcription factor 4 (KLF4), which maintains hTERT levels in human embryonic stem cells and cancer cells." (PMID 35348914, 2022). "Integrations occurred in the known cancer driver genes CCNA2, (four cases), TERT (one case), CCNE1 (three cases), TNFSF10 (two cases) and KMT2B (one case), leading to overexpression of the target genes." (PMID 36316711, 2022). "Furthermore, cancer-causing mutations in any of Ret Proto-oncogene (RET), neurotrophic tyrosine receptor kinase (NTRK), RAS, B-Raf proto-oncogene (BRAF), or telomerase reverse transcriptase (TERT) gene are linked to loss of thyroid-differentiating genes, including NIS." (PMID 35634509, 2022). "Kaplan–Meier curves generated for TERT demonstrate that for ALL, AML, and NBL cancer types, upregulation of TERT results in poorer prognoses." (PMID 36497424, 2022). "On the one hand, human TERT (hTERT) regulates cell proliferation and immortality and it is a potential TAA for immunotherapy since it is overexpressed by cancer cells." (PMID 35335881, 2022). "Given that the ETS family transcription factors GABPA and GABPB1 activate the mutant TERT promoter and induce TERT expression for telomerase activation, GABPB1 has been proposed as a cancer therapeutic target to inhibit telomerase." (PMID 35326537, 2022). "A total of 79 genes were found to have significant effects on prognosis based on their expression, and 23 genes had significant impacts on prognosis in at least two different cancer types, including C1R, RPL5, and TERT." (PMID 36497424, 2022). "In contrast, in healthy and cancer cell lines, intron-containing TUG1 and TERT RNAs were highly stable even after 4.5 h of transcription inhibition." (PMID 34083519, 2021). "First, using WGS and targeted sequencing of the TERT promoter provided in the CCLE, we assessed TERT promoter status for 503 cell lines across 21 cancer types." (PMID 34486523, 2021). "Higher activity of TERT has been reported in cancer cells and in most cells suffering from tumors while TRF1 provided a nucleotide sequence for TERT." (PMID 34679783, 2021). "Interestingly the two PTCs harboring both the TERT and BRAF mutations have a very different prognosis suggesting that the different germline mutational status may play a role in the modulation of cancer aggressiveness." (PMID 33821390, 2021). "To examine if this signature was LGG specific, we tested the correlation between the expression of signature genes (excluding TERT and TERC) and TERT in 32 cancer types." (PMID 33420056, 2021). "Taken together, our data indicate that GABPA and Sp1 synergistically activate mutant TERT promoter, contributing to tumorigenesis and cancer progression, particularly in the BRAFV600E-driven human cancers." (PMID 33483600, 2021). "Furthermore, as both LRP and TERT have been intricately linked to proliferation pathways like the MAPK pathway, knock-down of LRP and subsequently TERT and TRF-2, could severely impact the aggressiveness and rapid proliferation observed in cancer cells." (PMID 33836696, 2021). "Using cancer cell lines of various tissues of origin, we show that EXTEND outperformed TERT expression in predicting telomerase activity." (PMID 33420056, 2021). "Chromatin immunoprecipitation analyses revealed that in cancer, shelterin proteins (TRFs and RAP1) and TERT, apart from telomeric regions, also bind to intronic and distal promoter regions." (PMID 33599797, 2021). "Both TERT and TUG1 are upregulated in many cancers and thus represent important therapeutic targets." (PMID 34083519, 2021).
cancer (continued). "Telomerase reverse transcriptase (TERT) maintains telomere length and is known to be active in stem cells as well as cancer cells." (PMID 34207142, 2021). "Specifically, the 5p15.33 region, harboring the TERT and CLPTM1L genes, showed statistically significant local genetic correlations for multiple cancer pairs." (PMID 34355204, 2021). "Additionally, TERT has been shown to upregulate the expression of several matrix metallopeptidases—enzymes that are capable of extracellular matrix degradation—in a NFκB-dependent manner, suggesting that TERT has a NFκB-mediated role in cancer cell invasion and metastasis." (PMID 32599885, 2020). "The regions containing the TERT gene at chromosome 5p15.33 and the TERC gene at chromosome 3q26.3 are frequently amplified in cancers." (PMID 32121056, 2020). "Paradoxically, the TERT promoter CGI is primarily hypomethylated and inactive in healthy adult somatic cells, yet hypermethylated and active in cancer cells." (PMID 33245585, 2020). "Intriguingly, TERT promoter mutation in PTC is subclonal, while it is clonal in advanced cancers (PDTC and ATC), suggesting an advancement in TC due to a selected immortalized TERT-positive clone." (PMID 32231639, 2020). "Beyond its role as catalytic subunit of telomerase, TERT exerts several extra-telomeric functions; among these, transcriptional regulation of EGFR is of particular relevance, especially in cancer." (PMID 33553285, 2020). "Hypermethylation in this exonic region is common in most cancers, and CTCF is considered a major TERT repressor in normal cells." (PMID 33329574, 2020). "Additionally, while WT MAE and BAE lines associate with different cancer types —for example, pancreatic cancers are frequently WT MAE, while lung cancers are primarily WT BAE—it has been unknown whether there are associated TERT promoter methylation patterns." (PMID 33245585, 2020). "Moreover, TERT contributes to survival signaling, growth signaling, invasion/metastasis, angiogenesis, DNA methylation, genetic aberrations, and even to radio/chemo-resistance, which make TERT an important factor related to a higher aggressiveness of cancer cells." (PMID 32560331, 2020). "We identified several robust adjuvants whose addition to vaccine formulations resulted in enhanced T cell responses targeting the cancer antigens STEAP1 and TERT." (PMID 32161596, 2020). "Cancer-specific promoters such as telomerase reverse transcriptase (TERT), survivin, and chemokine receptor 4 (CXCR4) have enhanced activity in a variety of human and murine cancers, however, little has been published regarding these promoters in dogs." (PMID 33166332, 2020). "Pathways related to nervous system development (FDR = 5.8 × 10−8) were enriched for the PID-N genes ASCL1, CTNNB1, ID2, SUFU, and TERT that have known roles in cancer, complementing the PID-C genes NOTCH1, PTEN, and RHOA that also have known cancer roles." (PMID 32024854, 2020). "Interestingly, a recent study demonstrated that DNA hypermethylation within TERT promoter was prevalent and could upregulate TERT expression in various cancers 52, while the exact mechanism of the methylation pattern of TERT promoter in upregulating the TERT expression remains elusive." (PMID 33061812, 2020). "In particular, the TERT branch is affected by p21 (PTGES3) in LS-CRC, while in s-CRC cancers, we observe high influence of heat shock proteins (HSP90AB1 and HSPA1A)." (PMID 31750255, 2019).
cancer (continued). "In cancer Hela and MCF7 cells, export of endogenous TERT from the nucleus and import of TERT into mitochondria has also been observed after H2O2 treatment." (PMID 31781563, 2019). "TERT inhibition results in the disruption of the TERT-DNMT3B and TERT-β-catenin loop signals, thereby exerting detrimental effects on cancer cells." (PMID 31284662, 2019). "The levels of dyskerin in cancer cells modulate telomerase activity through the regulation of TERC levels, independently of TERT expression." (PMID 31157162, 2019). "Recently, RuvB-like 2 (RUVBL2) was found to interact with catenin beta 1 (CTNNB1), telomerase reverse transcriptase (TERT), MYC proto-oncogene (MYC), nuclear factor-kappa B1 (NFKB1), etc. to regulate the cancer-related signaling pathways in HCC." (PMID 31572066, 2019). "The most common adaptation of TERT promoter-driven gene therapy simply expresses various therapeutic moieties (anticancer transgenes, miRNA, or the CRISPR/Cas9 system) in a cancer-selective manner." (PMID 31035374, 2019). "Furthermore, the employment of BETi may present a selective strategy for targeting cancer cells presenting TERT promoter mutations sparing the ones that are not affected by these mutations, including normal cells." (PMID 31200515, 2019). "It is believed that such mutations activate telomerase activity by converting conserved regions within the TERT promoter into an ETS transcription factor, binding sites to permit the continuous cell divisions that are required for advanced cancers." (PMID 31159515, 2019). "When running CBaSe on our pan-cancer dataset, five out of nine genes detected as significant by CBaSe were also detected as significant by SSB-dN/dS (BCL2L12, TERT, AP2S1, KRI1, TMEM214)." (PMID 29855388, 2018). "Since BRD4 is considered the most important target of the BET inhibitor JQ1 in various cancers, we evaluated BRD4 protein expression in a series of UCCs compared to the benign urothelial control cell lines HBLAK, TERT-NHUC, and NHUC." (PMID 29312470, 2018). "The expression level of TERT transcript (mean ± SEM) was 28 ± 2.1, 25 ± 1.5, 30 ± 3.2 and 32 ± 4.1% in the untreated control MDA-MB-231, A-549, MCF-7 and U87-MG cancer cells, respectively." (PMID 30460096, 2018). "These mutations (− 124 bp C > T and -146 bp C > T upstream the TSS) represent the most prevalent non-coding alterations in cancer and create aberrant binding sites for E-Twenty-Six (ETS) TFs within the promoter, leading to increased TERT expression." (PMID 30466442, 2018). "The expression of TERT transcript by DEX treatment was significantly (P < .05) decreased in the A-549 and MCF-7 cancer cells with adiposome vesicles." (PMID 30460096, 2018). "However, the precise mechanism behind the TERT activation in cancers remained unknown." (PMID 28726783, 2017). "HDIs, TSA, depsipeptide and sodium butyrate, were shown to enhance the expression of genes such as CDKN2A, CDKN1A, SALL3, RARb2, TERT and GATA4 in human cancer cell lines by active DNA demethylation of their respective promoters." (PMID 28077797, 2017). "Recurrent mutations were identified in chromatin regulators and particularly ARID1A and ARID2 in HCCs and PDAs and in the TERT and TERT promoter locus in all kinds of HBP cancers." (PMID 28106782, 2017). "It is reported that genetic variations in telomere length related-genes TERT and TERC are involved in the many types of cancers." (PMID 29100352, 2017).
cancer (continued). "Histone Deacetylase Inhibitors (HDIs) have been shown to activate silenced genes including CDKN1A, CDKN2A,SALL3, RARb2, TERT and GATA4, in the human cancer cells by active DNA demethylation of their respective promoters." (PMID 28077797, 2017). "Previous studies have reported that a variety of genes regulated by CTCF, including RB1, TERT and BAX, are involved in proliferation and apoptosis in cancer cells." (PMID 28977939, 2017). "The TERT and TERC transcripts were highly expressed in A-549 and MDA-MB-231 cancer cells than in U87-MG cancer cells." (PMID 30460075, 2017). "One micrometer SMA exposure for up to 2 weeks induced significantly (P < .05) decreased expression level of TERT and TERC transcripts in each cancer cell line." (PMID 30460075, 2017). "Of the ‘Cancer census genes’ most frequently involved in a copy number gain, four were in common with those in the TCGA-data (i.e. FCGR2B, TERT, CD79B and PRKAR1A)." (PMID 29371938, 2017). "TERT, SDHA and RICTOR had the most frequent copy number gains (26.4%, 25.7% and 23.6% of all cases, respectively), with significant enrichment in carcinomas." (PMID 27873319, 2017). "To better understand the mechanism that leads to the telomerase-ALT switch in telomerase-positive cancer cells, we constructed different cell lines with specific telomeric DNA damage, ATRX knockdown, DAXX deletion or TERT KO." (PMID 27578458, 2016). "Importantly TERT may be upregulated in cancer-free patients in precursor lesions of GC." (PMID 27825130, 2016). "CDKN2A has length as the dominant determinant over amplitude in 6/8 cancers, while all 16 cancer types with MYC, CCND2, TERT, or AKT3 amplifications show low AUCs for both parameters." (PMID 26787600, 2016). "Several groups reported that TERT can form a complex with mTOR and other proteins such as PI3K/Akt, Hsp90 and S6 kinase in cancer cells." (PMID 27777385, 2016). "Comprehensive genomic characterization of HNSCC has frequently uncovered amplification of chromosome 5p, which encompasses TERT gene, in both HPV-positive and HPV-negative carcinomas." (PMID 27501725, 2016). "Furthermore, GWA studies of cancer risk have observed that variants in the TERT region influence risk for multiple cancer types, including breast, colorectal, lung, prostate and ovarian cancer, although these associations do not appear to all be driven by the same causal variant." (PMID 26138067, 2015). "In addition to maintaining telomere integrity, the TERT protein presents additional functions and has been shown to interact with NFκB and co-activate the expression of several genes, including cytokines, such as IL-6 and TNFα, which are critical for inflammation and cancer progression." (PMID 26143636, 2015). "Besides, functional and mechanistic studies have suggested that TERT acts as a direct transcriptional regulator of oncogenic signaling pathways that not only modulate its own levels but also control the induction of target genes critical for cell survival and cancer progression." (PMID 26020272, 2015). "As such, these findings will expand biological studies of the TERT/CLPTM1L region in this and other hormone-driven cancers." (PMID 25487306, 2015). "Although TERT showed a higher average methylation level in normal, adjacent CpGs of the CGI within TERT preferentially showed concordant methylation in cancer cells but a random methylated pattern in normal cells." (PMID 26659027, 2015). "Genetic variants near TERT are strongly associated with predisposition to eight or more different cancer types, suggesting a potential mechanism by which rs7736074 and rs4975596 could influence the oncogenic potential of the EGFR signaling pathway through modulation of TERT activity." (PMID 24152305, 2013). "Upon binding to telomerase reverse transcriptase (TERT) mRNA, the hairpin DNA within IONP@H1THs initiates self-assembly through hairpin DNA-mediated dimer formation, thereby enhancing magnetothermal properties of IONP@H1THs in cancer cells specifically." (PMID 41614641, 2026).
cancer (continued). "Understanding both canonical and non-canonical pathways of TERT is essential for comprehending its full spectrum of biological functions and its implications in aging, regenerative medicine, and cancer." (PMID 40243493, 2025). "TERC, the telomerase RNA, has been thought to be an unsuitable cancer marker because, unlike TERT mRNA, it is often expressed widely and occasionally even in the absence of telomerase activity." (PMID 40151802, 2025). "The frequently mutant TERT promoter (pTERT) forms de novo ETS family transcription factor binding sites and increases transcriptional activity in cancer cells by selectively recruiting ETS transcription factors, such as GABPA 3, ultimately activating telomerase and leading to cell immortalization." (PMID 40860184, 2025). "As TERT is highly expressed in the vast majority of cancer cells but largely absent in normal somatic cells, it represents an attractive and selective target for anti-cancer therapies." (PMID 40227701, 2025). "In those reports, several cancers that were RAS-negative turned out to carry BRAF, TERT or RET/PTC changes, showing that they could have been flagged by a broader gene panel." (PMID 41450928, 2025). "While we and others have shown that TERT expression in normal cells does not initiate cancer, telomerase becomes activated in 80% of cancer cells." (PMID 39975037, 2025). "An activator of the TERT gene without increasing incidence of cancer within animal models; T-lymphocyte proliferation in a telomerase-dependent manner in mice." (PMID 39858038, 2025). "This suggests that high levels of TERT may be involved in EAC oncogenesis, independently of telomere elongation activity, as reported for other types of cancer." (PMID 40955778, 2025). "The canonical and noncanonical activities of TERT confer upon cancer cells the ability to overcome limitations in cell division, endowing them with immortality and heightened resistance to various drugs." (PMID 40241101, 2025). "Additionally, molecular-docking analyses provided mechanistic insights into their potential interactions with key cancer-related proteins, including COX-2 and TERT, further supporting their anticancer potential." (PMID 40733037, 2025). "We have also described THOR as a cancer-associated epigenetic mechanism of hTERT upregulation, with unmethylated THOR repressing TERT promoter activity regardless of TERT promoter mutations (TPMs) status." (PMID 40558255, 2025). "Additionally, the non-canonical functions of telomerase reverse transcriptase (TERT) and TERRA appear to be involved in the epithelial-mesenchymal transition (EMT), which is important for cancer progression." (PMID 39222177, 2025). "Ubiquitination of TERT, another form of PTM, also occurs in human cancers." (PMID 38278800, 2024). "These cells will not undergo normal apoptosis; instead, increased TERT activity leads to so-called “cell immortality” and cancer progression." (PMID 39273661, 2024). "TERT, at aberrantly elevated levels, is a strong oncoprotein that promotes tumorigenesis and cancer aggressiveness involving its noncanonical telomerase-independent functions, including, prominently, the suppression of apoptosis." (PMID 38735658, 2024). "In conclusion, we demonstrate that the multi-cancer GWAS locus at 5p15.33 marked by rs10069690 and rs2242652 can be genetically and functionally accounted for by a combination of the SNP rs10069690 within intron 4 and a VNTR within intron 6 (VNTR6–1) of TERT." (PMID 39802763, 2024).